THNSL1 (threonine synthase like 1)
Synonyms: TSH1; FLJ22002
Tractability: PROTAC: ubiquitination databases record sites on it; its protein half-life has been measured.
Gene: Protein-coding gene on chromosome 10 (25,016,612 to 25,026,664, forward strand). Ensembl gene ENSG00000185875.
Subcellular location (Human Protein Atlas): Cytosol; Nuclear bodies; Mitochondria
Gene Ontology:
Cellular component: mitochondrion; cytoplasm
Genetic constraint (gnomAD): Loss-of-function variants: 55 observed, 59.05 expected, observed/expected ratio (o/e) 0.93, 90% interval 0.75 to 1.17. The upper end of that interval is the gene's LOEUF score, 1.17, which puts it in group 5 of 6, group 1 being the genes least tolerant of losing a copy. Missense variants: 896 observed, 921.89 expected, observed/expected ratio (o/e) 0.97, 90% interval 0.92 to 1.03. Synonymous variants: 309 observed, 325.19 expected, observed/expected ratio (o/e) 0.95, 90% interval 0.87 to 1.04.
Homologues: Orthologues: chimpanzee THNSL1 (99% identical), macaque THNSL1 (98% identical), dog THNSL1 (91% identical), pig THNSL1 (91% identical), mouse Thnsl1 (83% identical), rat Thnsl1 (82% identical), rabbit THNSL1 (80% identical), tropical clawed frog thnsl1 (64% identical), Caenorhabditis elegans cysl-1 (7% identical), Caenorhabditis elegans cysl-2 (6% identical), Caenorhabditis elegans cysl-3 (6% identical), Caenorhabditis elegans F13B12.4 (6% identical), and 3 more. Paralogues in human: CBS (11% identical), THNSL2 (10% identical), SDS (8% identical), SRR (7% identical), SDSL (7% identical).
Diseases named in the same sentence as THNSL1 in open-access papers:
THNSL1 is named in the same sentence as 1 disease in open-access papers, as found by Europe PMC text mining. Sharing a sentence is not in itself a finding about the gene and the disease.
THNSL1 shares sentences with these, for which no sentence is quoted: Crohn disease (1 paper).